FLT1 (fms related receptor tyrosine kinase 1)
Diseases named in the same sentence as FLT1 in open-access papers (continued):
Sharing a sentence is not in itself a finding about the gene and the disease.
preeclampsia (continued). "Alternating O2 concentrations combined with ARNT2 or BCL6 overexpression led to the dysregulation of 11 genes (5 in the M2 and 3 in the M1 modules), including LEP, FLT1, and ENG, similar to preeclampsia." (PMID 30135684, 2018). "On the other hand, Calretinin, HtrA, Flt-1, Nox4 and Endoglin were positively and Annexin XI and PLGF were inversely correlated with the severity of term preeclampsia." (PMID 25392996, 2014). "For example, Flt-1, HtrA, Calretinin, PAI-1 and EGFR were positively and PDEF, Annexin XI, PLGF and PCNA were inversely correlated with the severity of preterm preeclampsia." (PMID 25392996, 2014). "We observed several differentially methylated CpG sites in the promoter regions of VEGF, FLT-1 and KDR between the normotensive and preeclampsia groups." (PMID 23621880, 2013). "However, it may prove to be more informative when coupled with other biomarkers of PM, as is the case for preeclampsia, where the utility of sEng as a prognostic biomarker is strengthened when combined with measurements of soluble Flt-1 and placental growth factor." (PMID 21966395, 2011). "Another less known predictor of pregnancy complication is Flt-4 (also named as VEGFR3), a member of the VEGFR family and a relative to Flt-1 (VEGFR1), whose ratio with PlGF is widely used as a clinical predictor for impending preeclampsia and placenta related complications." (PMID 40698658, 2025). "Interestingly, the contribution of sENG to vascular pathology in preeclampsia is partially due to effects on NOS3; in concert with FLT1, ENG reduces placental angiogenesis and vasodilation of maternal spiral arteries, and increases vessel permeability." (PMID 37012406, 2023). "In summary, LEP, FLT1, RAB6C, and SASH1 were identified as potential biomarkers of preeclampsia." (PMID 37389124, 2023). "Our findings together with previous findings suggested COL17A1, FLT1, FSTL3, and SERPINA3 may influence the immune function of preeclampsia patients." (PMID 35528613, 2022). "The findings above present us with a rational hypothesis that autophagy activation accompanied by the changes of VEGFA and FLT1 could affect trophoblasts’ migration ability and protect against apoptosis under an ox-LDL–mediated preeclampsia-like condition." (PMID 34568425, 2021). "In preeclampsia, placental ischemia resulting from RUPP may stimulate upregulation of sFlt-1 by binding of hypoxia inducible factor (HIF) to the promotor of Flt-1 gene." (PMID 34681861, 2021). "As shown in our data, ox-LDL–treated HTR8/SVneo cells exhibited preeclampsia-like phenotypic changes: declined migration, impaired angiogenesis (VEGFA was downregulated and FLT1 upregulated), and apoptosis (Bax was upregulated), which were in accordance with the expression in the PE placenta." (PMID 34568425, 2021). "Likewise, the VEGF receptors VEGFR-1 (Flt-1) and VEGFR-2 (KDR/Flk-2) play roles in various vascular diseases, such as preeclampsia." (PMID 32260158, 2020). "The levels of Flt-1 in micro- and nano-vesicles from placentae affected by mild preeclampsia were not significantly different to those from normotensive placentae." (PMID 28790977, 2017). "Interestingly and in accordance with the role of hypoxia in preeclampsia, HIF1A can regulate the expression of several top DEGs identified in the meta-analysis including: LEP, FLT1, INHA, BHLHE40, SPAG4, HK2, HILPDA and ERO1L." (PMID 27802351, 2016). "CREBBP interacts with several proteins well known to be associated with preeclampsia, such as NFE2L2, LEP and VEGF/FLT1, but also with proteins not-yet related to preeclampsia." (PMID 26171964, 2015). "Increasing circulating soluble Flt-1, a soluble form of vascular endothelial growth factor (VEGF) receptor-1, which can bind both VEGF and placental growth factor (PGF), plays an important role in the pathogenesis of preeclampsia." (PMID 26588850, 2015).
preeclampsia (continued). "It seems that the increased expression of Flt1 could disturb VEGF-mediated function on trophoblast and endothelial cells in preeclampsia." (PMID 26221124, 2015). "In accordance with the altered trophoblast pathophysiology in early-onset preeclampsia, many of the most differentially regulated genes in women with preeclampsia (LEP, CGB, LHB, INHA, SIGLEC6, PAPPA2, and FLT1) have predominant or unique expression in the syncytiotrophoblasts." (PMID 24991435, 2014). "Our data indicates altered DNA methylation patterns in the VEGF, FLT-1 and KDR genes in preeclampsia as compared to the normotensive group, which could be involved in the pathophysiology of preeclampsia." (PMID 23621880, 2013). "FLT1, LEP, INHA and ENG genes were identified according to the literature, however, we also found other genes as FLNB, INHBA, NDRG1 and LYN highly significant but underexplored during normal pregnancy or preeclampsia." (PMID 24219996, 2013). "Hence, the occurrence and development of preeclampsia may be owing to the abnormal regulation of FLT1P1 and FLT1 expression; this indicates that FLT1P1 and FLT1 are promising biomarkers for the diagnosis of preeclampsia." (PMID 37389124, 2023). "We designed a series of experiments to show that autophagy activated by hypoxia could protect against the ox-LDL–mediated preeclampsia-like phenotype in HTR8/SVneo cells: migration declined, apoptosis (Bax was upregulated), and impaired angiogenesis (VEGFA was downregulated and FLT1 upregulated)." (PMID 34568425, 2021). "Among 167 proteins tested, the expression of 5 proteins (EGFR, Flt-1, Calretinin, PAI-1 and HtrA) were positively correlated and four proteins (AnnexinXI, PDEF, PCNA and PlGF) were inversely correlated with the severity of preterm preeclampsia (P<0.05, R value≥0.4)." (PMID 25392996, 2014). "Increasing circulating soluble Flt-1, a soluble form of vascular endothelial growth factor (VEGF) receptor-1 which can bind both VEGF and placenta growth factor (PGF), resulting impairment of angiogenic state was thought to be responsible for the pathogenesis of preeclampsia." (PMID 24073247, 2013). "The lack of measurement of flt-1 concurrently with VEGF in this study is considered a limitation as this may provide a good insight into the possible interaction between these factors on damage to endothelial cells in patients with preeclampsia." (PMID 36420291, 2022). "A recent single-cell transcriptomic study in human pregnancy revealed a cell-autonomous dysregulation of FLT1 and PLGF transcription in the syncytial trophoblast in early but not late preeclampsia." (PMID 38396719, 2024). "In preeclampsia, which is a non-PAS-like disorder but a typical abnormal placental disorder, the abnormal expression of Smad2 affects extrachorionic villus differentiation, which in turn affects soluble Flt-1 activity." (PMID 37762005, 2023). "Furthermore, the expression level of Flt-1(P<0.001) and PAI-1(P<0.01) were significant different in severe preterm preeclampsia women with or without adverse outcome." (PMID 25392996, 2014). "However, mean promoter CpG methylation could not account for the higher expression of FLT-1 and KDR in preterm preeclampsia as compared to normotensive group." (PMID 23621880, 2013).
breast carcinoma (132 papers, 1999 to 2025). "To validate our preclinical findings, we performed pFLT1 and FLT1 immunostaining on tissue specimens that were obtained prior to PARPi treatment from 10 breast cancer patients harboring mutations in the BRCA1/2 or PALB2 DNA damage response (DDR) genes." (PMID 38956205, 2024). "We show that FLT1 is activated in the tumor cells of PARPi-resistant tumors from Brca1- and Bard1-deficient models as well as from breast cancer patients." (PMID 38956205, 2024). "IL4 signaling in macrophages also transcriptionally regulated other genes causally associated with mammary cancer lung metastasis, including Ccl2, Csf1, Ccr1, Hgf and Flt1." (PMID 36077870, 2022). "On the one hand, it has been reported that Flt-1 overexpression improves survival in breast cancer, whereas KDR expression is associated with a poor prognosis." (PMID 15841074, 2005). "Although our sample size is small, these findings lay the foundation for future biomarker studies to test whether FLT1 activation in pre-treatment biopsies can be used to stratify breast cancer patients at high risk for rapidly acquiring resistance to PARPi." (PMID 38956205, 2024). "Furthermore, IL4 signaling in macrophages regulated the transcript abundance of several other genes already causally associated with mammary cancer lung metastasis including Ccl2, Csf1, Ccr1, Hgf and Flt1." (PMID 36077870, 2022). "The predictive power of the FFL (PDGF/FLT1/SHC1) in the PIK3CA-mutated luminal-A tumor patients demonstrated in this study could be further validated in other breast cancer cohorts when genome sequencing data for these cohorts are available in the future." (PMID 28392480, 2017). "However, another study has demonstrated, Flt-1 to be related to a higher metastatic and local recurrence risk in breast cancer patients." (PMID 15841074, 2005). "Specifically, we observed up-regulation of genes that drive breast cancer metastasis (IL13RA2, MMP3, PTGS1, SYK, VCAN, and FLT1) and downregulation of metastasis-associated suppressor genes (NOTCH3, and HTRA3)." (PMID 41179294, 2025). "Previous studies have revealed FLT1 expression in tumor cells of breast carcinoma, pancreatic, ovarian, and colorectal carcinoma." (PMID 39687450, 2024). "Here, we demonstrate that FLT1 signaling can potentially serve as a biomarker and therapeutic target to circumvent PARPi resistance in breast cancer patients." (PMID 38956205, 2024). "Here, we show that FLT1 activation in tumor cells is also clinically relevant, in this case by promoting PARPi resistance in breast cancer through a combination of cell-intrinsic and -extrinsic pathways." (PMID 38956205, 2024). "This is consistent with our finding that FLT1 activation in the tumor cells represents a key in-vivo determinant of PARPi resistance in our breast cancer models." (PMID 38956205, 2024). "Consistent with our preclinical studies, FLT1 activation in tumor cells at pre-treatment significantly correlates with shorter progression-free survival on PARPi in patients with breast cancer." (PMID 38956205, 2024). "First, in German Shepherd, we found downregulation of FLT1 gene (log FC = 6.7, p = 0.016) in mammary carcinoma tissue, compared to adjacent tissue in the metastasis-free group (n = 8)." (PMID 34679042, 2021). "Vascular endothelial growth factor (VEGF) promotes breast cancer progression by inducing angiogenesis via VEGF receptors on endothelial cells but also signals directly through receptors such as VEGFR-1 (Flt-1) expressed on tumor cells." (PMID 34680491, 2021). "A recent study of the expression of MMP-9 and VEGF(FLT1) in breast cancer patients found their correlation significant enough to propose these genes as prognostic indicators." (PMID 33909629, 2021). "MAMs promote cancer cell invasion and metastasis by FMS-like tyrosine kinase 1 (FLT1) receptor tyrosine kinase signaling in a mouse model of breast cancer." (PMID 33251232, 2020).
breast carcinoma (continued). "Some tumor cells can express Flt-1 or Flk-1, such as malignant melanoma, breast cancer and colorectal cancer." (PMID 29149180, 2017). "Flt1 expression has been found in tumor cells including breast cancer cells where FLT1 functions as a tumor growth regulator and pro-survival factor." (PMID 28423599, 2017). "Our results indicated that miR-507 represented potential therapeutic targets in breast cancer by modulating Flt-1." (PMID 27167339, 2016). "In this study, we determined that PlGF-1 and Flt-1 played a key role in migration and invasion of breast cancer." (PMID 27167339, 2016). "In this study, we discovered that PlGF-1 and Flt-1 played a key role in the migration and invasion of breast cancer." (PMID 27167339, 2016). "Clinical analysis indicated that miR-507 was negatively correlated with tumor differentiation, lymphatic metastasis, and the expression of Flt-1 in breast cancer." (PMID 27167339, 2016). "In summary, we showed that Flt-1 promoted the migration and chemotexis of breast-cancer cells by binding to PlGF-1." (PMID 27167339, 2016). "Functional assays showed that the expression of miR-507 was inversely correlated with the expression of Flt-1 and the invasive potential of breast cancer." (PMID 27167339, 2016). "More remarkably, our findings suggest a novel role for miR-507 in inhibiting Flt-1 expression and in suppressing the migration and invasion of breast cancer by inhibiting PlGF-1-induced actin polymerization." (PMID 27167339, 2016). "Flt-1 promoted lung colonization of human breast cancer with PlGF-1 stimulation, and miR-507 inhibited lung colonization of human breast cancer in animal experiments." (PMID 27167339, 2016). "Results showed that the breast-cancer cell line MDA-MB-231 had high levels of Flt-1, whereas MCF-7 cell expressed low levels." (PMID 27167339, 2016). "The results were consistent with the in vitro findings and indicated that Flt-1 induced the invasion of breast cancer by binding to PlGF-1, and miR-507 inhibited the invasion of breast cancer." (PMID 27167339, 2016). "These chemotaxis results indicated that Flt-1 played an important role in the PlGF-1-induced chemotaxis of breast-cancer cells." (PMID 27167339, 2016). "Intense reactivities to VEGF, flt-1 and flk-1 were observed in mammary cancer cells, especially in invasive mammary carcinoma." (PMID 10604730, 1999). "Western blot analysis confirmed the increase in flk-1 and flt-1 proteins in induced mammary cancers." (PMID 10604730, 1999). "Taking advantage of the animal model, we have demonstrated that mammary cancer cells expressed not only high levels of VEGF but also, surprisingly, its receptors (flt-1 and flk-1) in mammary cancer cells." (PMID 10604730, 1999). "Interestingly, MDH2 overexpression upregulated several genes associated with breast cancer metastasis (IL13RA2, MMP3, PTGS1, SYK, VCAN, and FLT1) and downregulated several genes associated with metastasis suppression (NOTCH3 and HTRA3)." (PMID 41179294, 2025). "As such, our preclinical studies might offer a new biomarker-guided combination treatment option that includes a PARPi (e.g., talazoparib) and a VEGFR inhibitor (e.g., axitinib) to specifically target PARPi-resistant breast cancers that express FLT1." (PMID 38956205, 2024). "Importantly, a retrospective series of breast cancer patients treated with PARPi demonstrated shorter progression-free survival in cases with FLT1 activation at pre-treatment." (PMID 38956205, 2024). "In addition, FLT1 signaling in macrophages activates an inflammatory response and promotes breast cancer metastasis." (PMID 38956205, 2024).
breast carcinoma (continued). "It is important to note that in our analysis, if using gene mutation data alone, none of the genes in the positively regulating FFL would have been identified, since the mutation frequency of PDGF-D, FLT1, and SHC1 are very low across all breast cancer samples." (PMID 28392480, 2017). "Flt-1 is also highly expressed in breast-cancer tissues and breast-cancer cell lines." (PMID 27167339, 2016). "By transfecting miR-507 into MDA-MB-231 and MCF-7 cells, we demonstrated that miR-507 could significantly repress Flt-1 protein expression and affect breast-cancer invasion." (PMID 27167339, 2016). "However, the molecular mechanism by which Flt-1 promotes breast-cancer invasion and metastasis by binding to PlGF-1 is unclear." (PMID 27167339, 2016). "Considering the role of Flt-1 in breast cancer, our results suggested that miR-507 could suppress breast-cancer invasion by directly targeting the 3′-UTRs of the Flt-1 genes." (PMID 27167339, 2016). "First, we detected the expression of Flt-1 in different breast-cancer cell lines." (PMID 27167339, 2016). "Results indicated that Flt-1 was the receptor of PlGF-1 on breast-cancer cells." (PMID 27167339, 2016). "However, the molecular mechanism by which Flt-1 promotes breast-cancer invasion and metastasis by binding to PlGF-1 is also unclear." (PMID 27167339, 2016). "Flt-1 promoted the migration and chemotaxis of breast-cancer cells by binding to PlGF-1." (PMID 27167339, 2016). "Hence, miR-507 appeared to negatively regulate tumor invasion and metastasis in breast-cancer patients by targeting Flt-1." (PMID 27167339, 2016). "First, we found that PlGF-1 and Flt-1 promoted the invasion and metastasis of breast-cancer cells." (PMID 27167339, 2016). "To determine whether Flt-1 affected the migration and invasion of breast-cancer cells by binding to PlGF-1, we performed wound healing and Transwell invasion assays." (PMID 27167339, 2016). "Overall, the biomarkers notably constitute genes that participate in breast cancer related pathways (e.g. marker genes involved in estrogen receptor pathway) and genes that were previously implicated in other cancer types (e.g. GSTP1, FLT1)." (PMID 19458770, 2007). "Collectively, our studies identify a previously unexplored role for FLT1 signaling in driving PARPi resistance in BRCA1/2-mutant breast cancers and suggest that pharmacological inactivation of FLT1 could greatly enhance the efficacy of PARPi treatment in patients." (PMID 38956205, 2024). "Thus, by circumventing the development of PARPi resistance in breast cancer patients, FLT1 blockade may serve to unleash the full clinical potential of PARPi therapy." (PMID 38956205, 2024). "Therefore, in vitro test on breast cancer cells harboring the active FFL (PDGF/FLT1/SHC1) using small molecule inhibitor drugs such as sunitinib, which also targets the PDGF receptors, could be an interesting validation experiment in the future." (PMID 28392480, 2017). "Thus, PlGF-1, Flt-1 and miR-507 may be useful prognostic markers for glioma and novel therapeutic targets for breast cancer." (PMID 27167339, 2016). "Our genetic experiments with FIt1 inhibition in cancer cells and the depletion experiments with VEGFR2 antibody allowed us to differentiate between the contribution of FLT1 and VEGFR2 to PARPi resistance in breast cancer." (PMID 38956205, 2024). "Using new PARPi-resistance models of Brca1- and Bard1-mutant breast cancer generated in-vivo, we identified FLT1 (VEGFR1) as a driver of resistance." (PMID 38956205, 2024).